MET (MET proto-oncogene, receptor tyrosine kinase)
Diseases named in the same sentence as MET in open-access papers (continued):
Sharing a sentence is not in itself a finding about the gene and the disease.
cancer (continued). "Aberrant activation of c-Met resulting from MET amplification and c-Met overexpression is associated with poor clinical outcome in multiple malignancies underscoring the importance of c-Met signaling in cancer progression." (PMID 26879245, 2016). "The analysis of MET gene copy number (CN) has been considered to be a potential biomarker to predict the response to MET-targeted therapies in various cancers." (PMID 26765781, 2016). "MET-positive cancer shows better results than MET-negative cancer when treated with MET inhibitor: MET expression is regarded as a useful biomarker of anti-MET treatment." (PMID 27296289, 2016). "Molecular docking supported that they bound well to c-MET and VEGFR2, which demonstrates that they are potential c-MET RTK inhibitors for cancer therapy." (PMID 27187326, 2016). "Elevated expression of both RON and c-MET in various tumors including breast and colon is associated with poor prognosis, suggesting a critical role for RON signaling in cancer cell survival, migration, angiogenesis and therapeutic-resistance." (PMID 26872377, 2016). "Preclinical studies have provided strong support for the notion that inhibitors of HGF/MET signaling have therapeutic efficacy in a selected group of cancer patients." (PMID 27121052, 2016). "Tivantinib (ARQ197) is a small molecule that inhibits MET tyrosine kinase receptor in MET-expressing cancer cells inducing cells apoptosis." (PMID 27433281, 2016). "Aberrant HGF/MET signaling supports cell survival, proliferation, angiogenesis, invasion and metastatic spread, which are essential hallmarks of cancer." (PMID 27121052, 2016). "In this study, we evaluated the feasibility of using a novel method of ddPCR to quantify the MET copy number or assess gene amplification from cancer samples consisting of cell lines or FFPE tumors." (PMID 26765781, 2016). "The expression of MET has been shown to be overexpressed and correlated with poor prognosis in a number of major human cancers including HCC." (PMID 27813498, 2016). "Aberrant HGF/MET signaling supports cell survival, proliferation, angiogenesis, invasion and metastatic spread of cancer cells, establishing HGF and MET as valid therapeutic targets." (PMID 27121052, 2016). "Numerous preclinical and clinical studies have demonstrated that antibody or small-molecule inhibitors targeting MET or HGF are effective anti-cancer therapies." (PMID 27013592, 2016). "Evaluation of membranous MET immunoreactivity in both cancer regions (center and periphery) was possible in 183 (76.3%) cases, of which 4 (2.2%) oropharyngeal SCC were HPV-16 positive." (PMID 26909606, 2016). "In this review, we discuss the importance of accurate HGF/MET signal detection as a predictive biomarker to guide patient selection for clinical trials of MET-targeted therapies in human cancers." (PMID 27013592, 2016). "We describe preclinical results that justify the clinical investigation of ABT-700 in cancer types with addiction to the MET oncogene." (PMID 26879245, 2016). "In many cancer cases, a combined treatment approach that targets both MET and other functionally redundant RTKs should also be considered." (PMID 27013592, 2016). "Various clinical trials were conducted to evaluate the safety and efficacy of selective HGF/MET inhibitors in cancer patients." (PMID 27013592, 2016). "Next, we analyzed 274 mutations in 24 cancer-relevant genes (Sequenom technology), including BRAF, NRAS, KIT c-MET, GNAS and GNAQ." (PMID 27057633, 2016). "Extensive evidences indicate that MET signaling is involved in the progression and spread of several cancers such as breast, liver, lung, ovary, kidney, and thyroid." (PMID 27557076, 2016). "Aberrant expression of ROS1, ALK or c-MET (RAM) is implicated in carcinogenesis and cancer drug resistance." (PMID 27136744, 2016).
cancer (continued). "Cancer cells addicted to the constitutively activated c-Met signaling driven by MET amplification undergo apoptosis upon exposure to ABT-700." (PMID 26879245, 2016). "The c-MET/HGF axis also inhibits apoptosis of cancer cells and confers resistance to cell death by conventional chemotherapy." (PMID 27917934, 2016). "The MET and EGFR receptors are actionable targets due to their high expression in TNBC; however crosstalk between MET and EGFR has been implicated in therapeutic resistance to single agent use of MET or EGFR inhibitors in several cancer types." (PMID 27655711, 2016). "Overall, these data suggest that ddPCR has the potential to detect the MET copy number in cancer cell lines or FFPE DNA and highly correlated with SNP 6.0 or FISH, respectively." (PMID 26765781, 2016). "And understanding of its role in disease has led to the development of Met as a major target in cancer drug and the development of a variety of MET pathway antagonists with potential clinical applications." (PMID 27557076, 2016). "Since c-MET mediates the interaction between cancer cells and mesenchymal cells of the bone microenvironment, we propose it as a suitable candidate to disrupt bone metastatic process." (PMID 27322553, 2016). "The aim of the current study is to investigate association between miR-199a rs74723057 and MET rs1621 and HCC risk in 1032 HCC patients and 1060 cancer-free controls." (PMID 27813498, 2016). "HGF/c-MET has been extensively studied as a therapeutic target in various cancers for the last two decades, especially in lung cancer therapy." (PMID 27923392, 2016). "The binding of HGF to its receptor MET activates signaling cascade which promotes the growth and survival of cancer cells and stimulates epithelial to mesenchymal transition (EMT), one of the early stages of metastatic spread." (PMID 27121052, 2016). "Constitutive activation of the MET pathway has been reported in various types of cancer, and promotes tumor cell proliferation, motility, invasion and metastasis." (PMID 25965822, 2015). "Analysis of the cancer cell lines shows a variable, but widespread expression of MET and FGFR2, which are receptors for HGF and FGF7, respectively, across the panel of ESCC cell lines." (PMID 25884729, 2015). "miR-130a has recently been shown to suppress cancer cell growth and invasion through targeting the proto-oncogene MET and several components in the mitogen-activated protein kinase (MAPK) pathway." (PMID 25544755, 2015). "Targeting HGF/c-MET signaling has provided valuable tools for the treatment of several malignancies and for overcoming drug resistance in cancer therapy." (PMID 28536400, 2015). "It have been proved that RON actively crosstalks with MET, and is essential to support the oncogenic phenotype of MET-addicted cancer cells." (PMID 26528757, 2015). "A number of novel HGF/MET-targeting agents, either as therapeutic proteins or as small molecules, has been tested in patients with cancer, and some of them showed encouraging results in clinical studies." (PMID 28536405, 2015). "Preclinically, MET inhibitors have been used to induce resistance via different mechanisms in different cancer types." (PMID 26381735, 2015). "In human HCC cell lines, c-MET positive cells were noted to have cancer stem cell-like characteristics." (PMID 28943627, 2015). "The role of c-MET in tumorigenesis through genetic aberration, up regulation of cellular cross talk, and roles in metastasis and activation of cancer stem cells is an area of ongoing research." (PMID 26097886, 2015). "Excessive activation of the hepatocyte growth factor/scatter factor (HGF/SF)-MET axis is considered to correlate with poor prognosis and drug resistance in various human cancers, including GC." (PMID 26528757, 2015). "While findings repeatedly emphasize the importance of targeting the MET pathway in primary and recurrent cancer, the strategies are shifting from monotherapy to multi-target therapy." (PMID 26381735, 2015).
cancer (continued). "Binding of HGF to c-MET leads to receptor dimerization and autophosphorylation resulting in the activation of multiple cellular processes that support cancer progression." (PMID 26404380, 2015). "Macroscopic and histological examination of isolated lungs 8 weeks after cancer cell injection showed that the total number of metastases in animals of the MET + MSCs group was significantly lower." (PMID 25888992, 2015). "Recent studies of other cancers show that MET amplification enables cancer cells to evolve and survive under therapeutic pressure, and that MET amplification confers radioresistance to cancer cells." (PMID 26909358, 2015). "The dysregulation of this pathway has been implicated in cancer initiation, development and even metastasis, which suggested that targeting to HGF/MET axis is a potential strategy in cancer targeted therapy." (PMID 26254225, 2015). "HGF/MET signaling appears to be a critical pathway in a variety of malignancies, and thus it has become a potential target for cancer therapeutics." (PMID 28536405, 2015). "We determined the cell-surface density of EGFR and c-MET in a panel of cancer cell lines grown under uniform conditions using flow cytometry." (PMID 26260789, 2015). "There are many studies evaluating the expression level of c-MET, but only few that investigated phosphorylated c-MET in human cancer tissues." (PMID 26215852, 2015). "For instance, circulating HGF was evaluated as a pharmacodynamic biomarker of MET inhibition by onartuzumab in patients with advanced cancers or with NSCLC." (PMID 28536405, 2015). "ADAM12, VCAN and MET protein expression levels were also detected through western blot in cancer cells transfected with miR-144 mimics." (PMID 25927670, 2015). "In a panel of previously defined MET amplified cancer cell lines MKN-45, GTL-16 and EBC-1, upregulation of sf-RON resulted in increased numbers of PF-resistant colonies." (PMID 26528757, 2015). "Taken together, these published reports support that CBZ has the capacity to modify a number of cell types in the bone microenvironment that contribute to both normal bone homeostasis and cancer-induced bone disease via the targeting of MET." (PMID 26279137, 2015). "Both mAbs and small-molecule HGF/MET inhibitors have shown clinical benefits in patients with cancer, and they are different in terms of pharmacological properties and their underlying mechanisms of action." (PMID 28536405, 2015). "This Phase 1 study (ARQ 197–116) was initiated based on the importance and prevalence of MET expression/over-expression in many cancer types and evidence of synergistic inhibition of tivantinib and sorafenib in vivo in several cancer cell lines." (PMID 25294187, 2015). "We dissect the potential use of new molecules that interfere with the HGF/c-MET axis as therapeutic targets for future clinical trials in cancer disease." (PMID 28536400, 2015). "We also dissect the potential use of new molecules that interfere with the HGF/c-MET axis as therapeutic targets for future clinical trials in cancer disease." (PMID 28536400, 2015). "On day 10 after the cancer cell injection, mice were injected via the tail vein with MSCs-luc2 cells (the MET + MSCs group)." (PMID 25888992, 2015). "The met proto-oncogene (MET), which is often amplified in human cancers and functions as an important regulator of cell growth and tumor invasion, was identified as a direct target of miR-144." (PMID 25927670, 2015). "Hepatocyte growth factor/scatter factor (HGF/SF) plays critical roles in cancer progression through its specific receptor, MET." (PMID 25268161, 2014). "Recently, the ability of SAIT301 to inhibit HGF-induced invasion and migration of nasopharingeal cancer cell lines has been described, suggesting a potential use for MET inhibitors in the treatment of this highly invasive and metastatic type of cancer." (PMID 28548076, 2014).
cancer (continued). "MET, originally identified as a proto-oncogene, was found to be up-regulated in a variety of cancers, inducing its constitutive expression." (PMID 28548073, 2014). "In cancer cells harboring gain-of-function alterations in MET, HER2, or Phosphatidyl-Inositol-3-Kinase (PI3K), catalytically inactive AKT (K179M) protected from drug induced cell death in a PH-domain dependent manner." (PMID 25551293, 2014). "CD44 and c-MET collaboration, and their interactions on the plasma membrane, lead to the activation of downstream signaling pathways that promote cancer progression." (PMID 24823486, 2014). "In the context of cancer therapeutic applications, the same general disadvantages reported for other mAbs are present also in the case of anti-MET mAbs." (PMID 28548076, 2014). "HGF is a pleiotropic factor involved in the enhancement of metastatic potential of cancer cells and MET encodes for its cellular receptor c-Met." (PMID 24952592, 2014). "It is therefore important to target MET along with a complementary target that can potentially synergize to kill cancer cells and ward off resistance." (PMID 25221930, 2014). "A recently developed c-MET inhibitor, INC280, has been shown to inhibit c-MET-dependent cell motility, proliferation, and invasion in several cancer cell lines in vitro and in vivo." (PMID 25098767, 2014). "The tight regulation of the HGF/MET pathway that is observed in development and regeneration is lost in cancer, and such deregulation occurs through multiple mechanisms." (PMID 25364819, 2014). "Of note, CD44v6 is a marker of cancer stem cells, functionally cooperating with MET to promote PI3K dependent metastatic growth." (PMID 28536396, 2014). "The DN-30 mAb is a partial MET agonist, but also behaves as an antagonist, and has been further developed as a monovalent antibody for anti-cancer therapy (see Antagonist MET mAbs section)." (PMID 28548076, 2014). "The observation that MET is a proto-oncogene and that its signaling is often subverted in cancer has promoted deep investigations on its molecular structure and signaling proprieties which are reviewed herein." (PMID 28536396, 2014). "Specifically, we examined sensitivity of cancer cells in the presence of mutations and/or over-expression of BRAF, CDH1, ERBB2, CCND1 and MET." (PMID 24884660, 2014). "This concept is now being pursued as a strategy for cancer therapy through the use of a monoclonal antibody (see further information in the antagonist MET antibodies section)." (PMID 28548076, 2014). "Abnormal expression of c-MET induces multiple signal transduction pathways involved in cancer growth and metastasis including the RAS, PI3K, STAT3, and β-catenin pathways." (PMID 25339972, 2014). "c-MET inhibitors have shown antitumor efficacy in preclinical studies and are currently being evaluated in human cancer clinical trials." (PMID 25098767, 2014). "Another major target of let-7a is c-MET, which is one of the key genes activated by L1 expression in cancer cells." (PMID 25339972, 2014). "Third, we identified several novel and recurrent kinase fusions that very likely play a role in cancer, such as those involving the MET proto-oncogene and PIK3CA (phosphatidylinositol-4,5-bisphosphate 3-kinase, catalytic subunit alpha)." (PMID 25204415, 2014). "Aberrant MET activation plays important roles in cancer cell survival, growth, angiogenesis, and metastasis in various cancers including lung, breast, kidney, and gastrointestinal tract malignancies." (PMID 25364819, 2014). "Cabozantinib, an inhibitor of MET and other RTKs is in clinical trials for a variety of cancers with deregulated RTK signaling." (PMID 24743024, 2014). "Some reports have demonstrated that Crizotinib inhibited the proliferation and growth by inhibiting c-MET signaling in c-MET altered cancers." (PMID 25193856, 2014). "The high frequency of expression in prostate and other cancer types makes c-MET an attractive potential therapeutic target." (PMID 23251249, 2013).
cancer (continued). "Accordingly, multiple novel MET inhibitors are being developed against various cancers, including PCa." (PMID 24205338, 2013). "The degree of serum HGF and MET expressions in cancer tissues correlates with the prognosis of patients." (PMID 23296269, 2013). "The hepatocyte growth factor receptor (MET) is a receptor tyrosine kinase (RTK) that has emerged as an important cancer target." (PMID 24265843, 2013). "The human receptor tyrosine kinase MET and its ligand hepatocyte growth factor/scatter factor are essential during embryonic development and play an important role during cancer metastasis and tissue regeneration." (PMID 23731667, 2013). "The mammalian target of rapamycin (mTOR), is a downstream conduit of EGFR and MET signaling, and is thus considered a therapeutically attractive target in the treatment of various types of cancers." (PMID 23690929, 2013). "These mutants clearly suppress HGF-induced cancer cell migration via the inhibition of MET tyrosine phosphorylation." (PMID 23296269, 2013). "Diminution of phosphorylated MET and associated decreases in ERK1/2 and AKT phosphorylation has been shown to be important in growth, migration and cell survival pathways for other cancer cell types." (PMID 24326130, 2013). "MET and its ligand, hepatocyte growth factor (HGF), have been implicated in the progression of many cancers." (PMID 24205338, 2013). "Among them, the following well-known cancer genes were found: MET, CDK4, MDM4, EGFR and PIK3CA (amplifications), and CDKN2A, MLLT3, HRAS, CARS and NF1 (deletions)." (PMID 23408991, 2013). "Aberrant MET activation occurs in many human cancers, correlates with poor prognosis, and is considered an important candidate for targeted therapy." (PMID 22166800, 2012). "Because of its ubiquitous role in cancer, the MET axis makes it an attractive target for cancer therapy." (PMID 23320251, 2012). "Although NaBu is regarded as a potential anti cancer substance, the endogenous expressing c-MET cancer stem cell population survived after the treatment of NaBu." (PMID 22253909, 2012). "In this regard, MET inhibitors have raised a broader interest in their therapeutic indications in cancer." (PMID 22489192, 2012). "Based on this result and other studies, the MET expression level is different between the two cancer cell lines, MCF-7 and MDA-MB-231." (PMID 22253909, 2012). "The p170 c-MET was observed on the surface of three different cancer cell lines (A549, LoVo and U87MG) as determined by FACS using all three antibodies." (PMID 22511956, 2012). "HGF then binds with its cognate receptor, c-MET, which is expressed by normal and cancer stem cells." (PMID 22438903, 2012). "Studies have illustrated that MET, an oncogene that promotes the progression and invasion of cancer cells, contributes to the cell proliferation by minimizing the apoptosis." (PMID 22253909, 2012). "Because of its ubiquitous role in cancer, the MET axis seems to be an attractive target for cancer therapy." (PMID 23320251, 2012). "Taken together, these studies show that regulation of MET signaling by proteases is relevant in the context of cancer." (PMID 22973229, 2012). "Inappropriate activation of the MET oncogene has been reported in a wide variety of human tumors, where it supports execution of pathological invasive growth, leading to cancer aggressiveness and metastatic dissemination." (PMID 22973229, 2012). "The importance of the reverse regulation, i.e., modulation of MET (or other receptor tyrosine kinases) by proteases, became apparent only recently, but proved to be relevant for the development of new cancer therapies." (PMID 22973229, 2012). "In support of our findings, the expression of miR-199a-3p was significantly reduced in several cancers, and restoring the level of miR-199a-3p induced growth suppression via regulation of mTOR and MET." (PMID 22550419, 2012).